REN (renin)
Diseases named in the same sentence as REN in open-access papers (continued):
Sharing a sentence is not in itself a finding about the gene and the disease.
Hyperkalemia (continued). "While aldosterone levels in PHA2 can be variable, they are typically low for the degree of hyperkalaemia, due to the hypervolemia with suppressed renin." (PMID 39527282, 2025). "The presence of persistent hyperkalemia, hyperchloremic metabolic acidosis with a normal anion gap, and suppressed plasma renin activity prompted genetic investigation, ultimately confirming the diagnosis." (PMID 40530196, 2025). "ADTKD–REN involves CKD with reduced renin production, leading to mild hypotension, hyperkalemia, childhood anemia, hyperuricemia, and recurrent acute kidney injury (AKI)." (PMID 39976632, 2025). "It typically presents in neonates or infants with hyponatremia, hyperkalemia, elevated renin and aldosterone levels, and occasional metabolic acidosis." (PMID 40648780, 2025). "Recent studies suggest that combining potassium-retaining diuretics, renin-angiotensin system inhibitors, and sodium-glucose cotransporter 2 inhibitors (SGLT2i) reduces the incidence of hyperkalemia." (PMID 41458378, 2025). "A strong correlation between PAC and renin was observed in the overall cohort, particularly among individuals with hyperkalemia." (PMID 41517465, 2025). "Eleven of 150 patients (7.3%) had hyponatremia at T0 (mean renin 363.9 ± 194.8 mIU/L), while 6 patients had hyperkalemia (mean renin 408.6 ± 420.2 mIU/L)." (PMID 39416427, 2024). "On the other hand, drugs that interfere with the renin-angiotensin-aldosterone axis can also induce hyperkalemia by decreasing tubular potassium excretion." (PMID 38292832, 2024). "Nevertheless, we would like to point out that all patients with hyponatremia and/or hyperkalemia had very high renin levels (well above the accepted standards), which allows us to exclude interlaboratory differences on this point." (PMID 39416427, 2024). "In summary, disturbance in potassium excretion from low GFR or medications/conditions that interfere with renin-angiotensin-aldosterone activities would result in hyperkalemia." (PMID 38292832, 2024). "Cardiovascular conditions like arrhythmia triggered by hyperkalaemia can lead to life-threatening events, and the discontinuation of renin-angiotensin-aldosterone system inhibitors (RAASi) contributes to increased mortality in patients with CKD." (PMID 38404365, 2024). "The cases exhibited hyponatremia, hyperkalemia, acidosis, and activated renin-angiotensin II-aldosterone system." (PMID 38985174, 2024). "Renin-angiotensin-aldosterone system inhibitor (RAASi) therapy provides cardiorenal protection but is often downtitrated or discontinued after a hyperkalemia episode." (PMID 39167454, 2024). "Plasma renin levels are usually suppressed and aldosterone levels can be variable but are relatively low due to the hyperkalemia." (PMID 36726778, 2023). "Overall, these findings suggest that hyperkalemia entails the underdosing or discontinuation of renin–angiotensin–aldosterone system inhibitors, which is associated with poorer clinical outcomes beyond the potential arrhythmogenic effects." (PMID 37240702, 2023). "Hyperkalemia is often the result of the use of RAAS (the renin-angiotensin-aldosterone system) blockers, mineralocroticode receptor antagonists, or potassium-sparing diuretics." (PMID 36553138, 2022). "In this setting, the use of drugs interfering with RAAS would more easily trigger hyperkalemia than in subjects with a normal renin level." (PMID 36303866, 2022). "The most common documented reason for deferring renin-angiotensin inhibitors or mineralocorticoid receptor antagonists was acute renal failure, followed by allergy, including angioedema, followed by hyperkalemia." (PMID 35720679, 2022). "Major adverse events that were significantly higher in the direct renin inhibitor group were hyperkalemia and hypotension." (PMID 36204481, 2022). "The expected abnormalities are low aldosterone levels, hyperkalemia and elevated renin; however, because renin levels are age-specific appropriate references should be used." (PMID 35992119, 2022).
Hyperkalemia (continued). "Healthy elderly people are known to have lower basal and stimulated aldosterone and renin levels than young people, and the response to hyperkalemia of the former is less effective than that of the latter." (PMID 36303866, 2022). "The treatment of hyperkalemia often leads to the discontinuation or restriction of beneficial but potassium-increasing therapy such as renin-angiotensin-aldosterone inhibitors (RAASi) and high-potassium diet including fruits and vegetables." (PMID 36364890, 2022). "As decreased renin activity is accompanied by low blood pressure and hyperkalemia, treatment is required and includes fludrocortisone." (PMID 36362756, 2022). "In order to reduce the risk of hyperkalemia, discontinuation of potassium supplements and reduction of RAAS inhibitors must be anticipated when suppressed renin renders intensification of MRA therapy." (PMID 33841329, 2021). "The heterogeneity between studies assessing acute kidney injury and hyperkalaemia events was reduced when focusing on drugs that affect the renin angiotensin-aldosterone system." (PMID 33568342, 2021). "The condition of high plasma renin level with inappropriate normal range of Ald, hyperkalemia and hyponatremia raising the suspicion of ASD." (PMID 34243750, 2021). "For example, the SARS-CoV-2 can induce hyperkalemia through influence on the renin–angiotensin–aldosterone pathway." (PMID 34975830, 2021). "Simultaneously with the escalation of MRA doses, adjustments of other medications that influence eGFR and/or serum potassium concentrations are essential to prevent hyperkalemia while attempting to reverse renin suppression." (PMID 33841329, 2021). "The prescription of drugs such as angiotensin-converting-enzyme (ACE) inhibitors, angiotensin II receptor blockers (ARBs), potassium-sparing diuretics, and renin inhibitors tends to intensify hyperkalemia." (PMID 30048562, 2019). "Similarly, clinicians may have been cautious in prescribing trimethoprim to those at highest risk of acute kidney injury and hyperkalaemia, again leading to an underestimation of the true risk of adverse outcomes, particularly for those taking renin-angiotensin system blockers." (PMID 29438980, 2018). "Gordon Syndrome (GS) was described in the 1960s and is a very rare familial hypertension syndrome that presents with low renin and hyperkalemia." (PMID 29439489, 2018). "Although hyperkalemia, hyponatremia and metabolic acidosis in these patients suggest hypoaldosteronism, their plasma aldosterone and renin activity are high." (PMID 28286482, 2017). "Laboratory tests revealed hyponatremia, hyperkalemia, and metabolic acidosis with high renin and low aldosterone." (PMID 29201470, 2017). "In fact, in these patients, hyperkalemia can be often determined by the use of aldosterone antagonists (especially for high doses) or, to a lesser degree, of inhibitors of the renin angiotensin aldosterone system drugs, or a combination of both." (PMID 28106712, 2017). "It is characterized by hyperkalemia, hyponatremia, metabolic acidosis, and high plasma aldosterone and renin concentrations." (PMID 26904317, 2016). "Patiromer and zirconium cyclosilicate are attractive agents that are expected to prevent hyperkalemia during renin-angiotensin-aldosterone system inhibition, and serelaxin and urodilatin are promising drugs in the treatment of acute heart failure." (PMID 26918130, 2015). "Both autosomal dominant and recessive forms of PHA1 are characterised by salt wasting and hyperkalaemia with increased plasma renin and aldosterone levels, reflecting a resistance of the kidney and other tissues to mineralocorticoids." (PMID 25276129, 2014). "A typical biochemical profile of this disorder includes hyponatraemia, hyperkalaemia, raised plasma renin activity, undetectable or low aldosterone level, and normal or elevated cortisol levels." (PMID 24694176, 2014).
Hyperkalemia (continued). "PHA type 2 (PHA2) represents a group of conditions commonly characterised by hyperkalaemia despite normal renal glomerular filtration, metabolic acidosis, and a low plasma renin level, with high incidence of hypertension." (PMID 25276129, 2014). "According to a previous review of heparin-induced hyperkalemia, renin activity remains constant or rises and is infrequently accompanied by hyponatremia." (PMID 24932609, 2014). "The salt loss is restricted to the kidney, and biochemically, it is characterised by salt wasting, with hyponatraemia, hyperkalaemia and a metabolic acidosis, with elevated plasma renin and aldosterone levels." (PMID 24616761, 2013). "The renal abnormalities that manifest in hyperkalemia can be grouped as follows: renal tubular secretory abnormalities, impaired renin-aldosterone axis, drug-induced hyperkalemia, decreased distal tubular flow with low sodium, and renal failure." (PMID 23882341, 2011). "Furthermore, a number of drugs may impair signalling in the renin–angiotensin-aldosterone system and cause hyperkalemia and metabolic acidosis (e.g. potassium sparing diuretics, trimethoprim, cyclo-oxygenase inhibitors, angiotensin converting enzyme inhibitors)." (PMID 19721811, 2009). "Laboratory workup revealed hyperkalemia, suppressed aldosterone, elevated renin, and low androgens." (PMID 40860571, 2025). "Sparsentan’s renin–angiotensin system (RAS)-replacement model offers a streamlined mechanism of action but may carry a slightly higher risk of edema and hyperkalemia." (PMID 41050133, 2025). "Primary pseudo-hypoaldosteronism is a rare autosomal hereditary disorder marked by resistance to aldosterone, leading to renal salt wasting, hypovolemia, tendency to low blood pressure, hyponatremia, hyperkalemia, metabolic acidosis, and elevated renin and aldosterone levels." (PMID 38985174, 2024). "The renin–angiotensin–aldosterone system often affects the regulation of such precursors, with renin increasing in patients with hyperkalaemia, and mineralocorticoid receptor antagonist (MRA) antihypertensives and spironolactone needing to be paused before testing for renin function." (PMID 37241010, 2023). "In this cohort study, liver disease was an independent risk factor strongly associated with recurrent hyperkalemia within 1 year, independent of concomitant renin-angiotensin-aldosterone system inhibitor or potassium-sparing diuretic use." (PMID 37510679, 2023). "The prevalence of hyperkalemia is 2–3% in the general population, whereas notably higher frequencies of hyperkalemia have been reported in patients with diabetes, advanced kidney disease, and those treated with renin-angiotensin-aldosterone inhibitors (RAASi)." (PMID 36364890, 2022). "The presence of hyperkalaemia limits the use of renin-angiotensin-axis inhibitors." (PMID 34979961, 2022). "Laboratory results revealed hypoglycemia, hyponatremia, and hyperkalemia with increased renin activity, increased adrenocorticotropic hormone (ACTH), low aldosterone, low cortisol, high dehydroepiandrosterone sulfate (DHEAS), and high 17 hydroxyprogesterone levels." (PMID 36106234, 2022). "Modulators of this aldosterone-independent mechanism for K+ secretion might provide new avenues for treating hyperkalemia, particularly when induced by inhibitors of the renin–angiotensin–aldosterone system." (PMID 36373794, 2022). "Because hypovolemia and concomitant hyponatremia and hyperkalemia indicate a combination of impaired sodium, potassium, and water handling — and because these abnormalities stimulate renin, angiotensin, and aldosterone secretion — we anticipated that plasma aldosterone would also rise." (PMID 35104250, 2022). "It should be noted that constipation and administration of a renin–angiotensin system inhibitor in patients with renal failure may contribute to refractory hyperkalemia and should thus be handled with caution." (PMID 34063969, 2021).
Hyperkalemia (continued). "The normal ald level in ASD patients may be the result of compensation of Ald secretion due to hyponatremia and hyperkalemia and neonatal hyperactivity of renin-angiotensin-aldosterone system." (PMID 34243750, 2021). "In this analysis, we observed that SZC therapy improves hyperkalemia and may allow for a higher likelihood of up-titration of renin–angiotensin–aldosterone system inhibitors, which would indirectly have facilitated reverse cardiac remodeling." (PMID 34884224, 2021). "For acute kidney injury and hyperkalaemia events, the observed heterogeneity was partly explained by pooling of different drug classes, and heterogeneity was reduced when we focused on drugs that affect the renin angiotensin-aldosterone system." (PMID 33568342, 2021). "The occurrence of these side effects might be worse in the elderly population, as they are prone to developing acute kidney injury and hyperkalemia due to the risk of complete RAS inhibition, as they already have low plasma renin levels." (PMID 34830315, 2021). "As the stage of CKD advances, hyperkalemia may develop because of a reduction in urinary potassium excretion and an increase in the frequency of administration of renin-angiotensin system antagonists." (PMID 31752746, 2019). "While this may seem counterintuitive for renin-angiotensin system inhibitors, these agents may be avoided because of fear of complications such as hyperkalemia or acute kidney injury, especially in acute care settings." (PMID 31860111, 2019). "There is an additional increase in the odds of hyperkalaemia after a UTI for those prescribed renin-angiotensin system blockers, and greater than sixfold increase in association with concomitant use of a potassium-sparing diuretic, regardless of antibiotic choice." (PMID 29438980, 2018). "However, for people taking renin-angiotensin system blockers and spironolactone treatment with trimethoprim instead of amoxicillin there were 18 additional cases of hyperkalaemia and 11 admissions with acute kidney injury." (PMID 29438980, 2018). "However, treatment with both renin-angiotensin system blockers and potassium-sparing diuretics would result in 18 additional cases of hyperkalaemia and 11 of acute kidney injury." (PMID 29438980, 2018). "Subjects with GS have suppressed renin levels consistent with their high volume state, with relatively low aldosterone levels (that may still fall in the reference range) despite their hyperkalemia, that can be occasionally severe and with periodic paralysis." (PMID 29439489, 2018). "Gadallah reported a case in which unilateral adrenalectomy for adrenal adenoma was followed by severe hyperkalemia, marked volume depletion and undetectable plasma renin activity and serum aldosterone suggesting chronic suppression of the renin-aldosterone axis." (PMID 27460219, 2016). "The following laboratory findings are suggestive of HRS: elevated plasma renin activity, elevated plasma noradrenaline activity, hyponatraemia, hyperkalaemia, elevated blood urea nitrogen, decreased plasma osmolality, elevated urinary osmolality, and decreased urinary sodium excretion." (PMID 25649410, 2015). "Hyporeninemic hypoaldosteronism as a consequence of prostaglandin inhibition by indomethacin may be considered as a possible mechanism for the development of the hyperkalemia, since prostaglandins are potent stimuli for renin release." (PMID 24932609, 2014). "All subjects had hyperkalaemia, hyponatraemia, with elevated renin and aldosterone levels." (PMID 24616761, 2013). "MRAs such as finerenone are known to increase serum potassium levels, but early combination with either an SGLT2i22 or ARNI23 (when switched from a renin–angiotensin system inhibitor) may attenuate risks of hyperkalemia, suggesting that these combinations may in fact be safer." (PMID 41052644, 2026).
Hyperkalemia (continued). "Of note, although the incidence of hyperkalemia was slightly higher in finerenone group than placebo group, not many patients permanently discontinued the drug due to hyperkalemia (122/7331≈1.66%), which is significantly lower than the data on renin-angiotensin system blockers." (PMID 40678143, 2025). "Notably, hyperkalemia induces aldosterone secretion independently of the renin-angiotensin system." (PMID 40369054, 2025). "However, the addition of neprilysin inhibition does not appear to elevate the risk of hyperkalemia in patients already receiving renin-angiotensin-aldosterone system inhibitors." (PMID 39301489, 2024). "Moreover, hyperkalemia may preclude the optimization of renin-angiotensin system blockade, a key kidney protective maneuver." (PMID 39458940, 2024). "Furthermore, all patients with hyponatremia and/or hyperkalemia had very high renin levels." (PMID 39416427, 2024). "Therefore, renin–angiotensin–aldosterone system (RAAS) inhibitors remain the first-choice treatment to prevent progression of CKD; however, their use is limited by the risk of hyperkalemia and acute kidney injury." (PMID 35583597, 2022). "Furthermore, medications such as potassium‐sparing diuretics, MRAs, ACE inhibitors, ARBs, direct renin antagonists, β‐blockers, nonsteroidal anti‐inflammatory drugs, heparin, and penicillin are associated with hyperkalemia." (PMID 36574588, 2022). "Blood exams showed hyponatremia, hyperkalemia, normal serum basal cortisol with increased ACTH and renin, while urinary metanephrines were within the range of normality." (PMID 36290900, 2022). "Following the reduction of hyperkalemia by SZC therapy, renin–angiotensin–aldosterone system inhibitors were up-titrated in this study." (PMID 34884224, 2021). "His hyponatremia, hypotension, and hyperkalemia pointed to a picture of adrenal insufficiency confirmed by undetectable serum cortisol, elevated ACTH, renin, and low aldosterone levels and imaging." (PMID 34976418, 2021). "In newborns, blood tests showed severe hyponatremia, hyperkalemia, extremely elevated levels of ACTH, and renin activity with low or inappropriately normal levels of cortisol and aldosterone." (PMID 33415088, 2020). "The potential benefits of renin–angiotensin–aldosterone system (RAAS) blockers in elderly patients must be weighed against the potential risks of acute kidney injury and hyperkalemia due to age-related reductions in serum renin and aldosterone levels." (PMID 26512568, 2015). "While there was definite hyponatremia and increased aldosterone and renin levels, and it presented with failure to gain weight, the hyperkalemia was mild, and the infant was not dehydrated, nor did it present a skin or pulmonary phenotype." (PMID 40969802, 2025). "It is important to note that all patients with hyponatremia and/or hyperkalemia had very high renin levels and none of them had renin levels in the normal range." (PMID 39416427, 2024). "Plasma renin, angiotensinogen, angiotensin-I, angiotensin-II, and aldosterone were measured to assess the role of the RAAS axis in volume-related lower blood pressure and hyperkalemia." (PMID 36803854, 2023). "It has been reported that older individuals have lower plasma renin and aldosterone levels compared with younger controls, with impaired responses to RAAS stimuli, such as sodium depletion, hyperkalemia, and upright posture, in older individuals (especially in late-elderly individuals)." (PMID 36843595, 2023). "Therefore, we categorized the ICI-PAI cases from the FAERS into “confirmed PAI” and “suspected PAI” based on the reported terms of hyperkalaemia and increased ACTH or renin." (PMID 35870109, 2022). "Hyperkalemia represents a frequent complication of CKD progression, limiting the therapeutic strategies options recommended for treatment and prevention of cardiovascular disease (CVD), including renin-angiotensin-aldosterone inhibitors (RAASi)." (PMID 34150795, 2021).